CLN3 (CLN3 lysosomal/endosomal transmembrane protein, battenin)
Diseases named in the same sentence as CLN3 in open-access papers (continued):
Sharing a sentence is not in itself a finding about the gene and the disease.
metabolic disease (3 papers, 2018 to 2025). A congenital disorder (due to inherited enzyme abnormality) or acquired (due to failure of a metabolically important organ) disorder resulting from an abnormal metabolic process. "In this study, we demonstrate that quantifying lymphocyte vacuolization—either manually or using FACS analysis—both allows to rapidly diagnose vacuolization‐associated metabolic disease and to classify disease severity, particularly CLN3 disease." (PMID 32685355, 2020). "JNCL is an uncurable inherited metabolic disorder caused by CLN3 mutation." (PMID 39917569, 2025). "This might greatly accelerate therapy development for CLN3 disease as well as other metabolic disorders that are currently without treatment." (PMID 32685355, 2020).
brain disease (1 paper, 2023).
cardiac disease (1 paper, 2023). "Pathological investigation of these structures in NCL disorders which have a high incidence of cardiac disease, such as CLN3, has demonstrated an accumulation of ceroid lipopigment." (PMID 36831752, 2023).
myopathy (1 paper, 2025). A disease of the muscle in which the muscle fibers do not function properly. "Consistent with this hypothesis, we recently described progressive neuromuscular pathology and myopathy in CLN3 disease, with denervation of the neuromuscular junction (NMJ), loss of NMJ terminal Schwann cells, and marked atrophy of skeletal myofibers in Cln3Δex7/8 mice." (PMID 41430350, 2025).
CLN3 also shares sentences with these, for which no sentence is quoted: CLN3 disease (5 papers); Fabry disease (3); Ataxia (2); CLN5 disease (2); CLN6 disease (2); epilepsy syndrome (2); generalized epilepsy (2); iron deficiency (2); Obesity (2); sphingolipidoses (2); aspartylglucosaminuria (1); autoimmune disease (1); autonomic dysfunction (1); Charcot-Marie-Tooth disease (1); Charcot-Marie-Tooth disease type 1A (1); childhood dementias (1); choroideremia (1); chronic kidney disease (1); CLN8 disease (1); Coffin-Siris syndrome (1); colorectal adenocarcinoma (1); cone-rod dystrophy (1); Congenital disorder of glycosylation, type Iq (1); congenital muscular dystrophy (1); connective tissue disorder (1); cystinosis (1); Danon disease (1); developmental and epileptic encephalopathy (1); Farber disease (1); Gaucher disease (1).
A further 40 diseases each share a sentence with CLN3 in 1 paper.